GZMB (granzyme B)
Diseases named in the same sentence as GZMB in open-access papers (continued):
Sharing a sentence is not in itself a finding about the gene and the disease.
tumor (continued). "Our results also suggest that the CD4+ T-cell-mediated anti-tumor response may not substantially require FasL and GzmB expression." (PMID 39885128, 2025). "Additionally, we found more tumor-specific T cells with a stem-like (TCF1+ TIM3- PD1+) and a transitory (TCF1- TIM3+ CD101- PD1+) exhausted phenotype and more expressing effector molecules such as GzmB, IFNγ, and TNFα." (PMID 38646638, 2024). "Moreover, they found that patients injected with anti-PD-1 exhibited downregulation of HLA-I expression, while the expression of CTL and GZMB was not significantly different from that of normal individuals, potentially contributing to tumor immune tolerance." (PMID 39456702, 2024). "Similarly, ELISA results showed consistently increased granzyme B and perforin in the tumor-grinding fluid of mice injected with TREM2 KO monocytes, indicating that TREM2 promotes tumor growth in vivo by increasing the number of M2-TAMs and inhibiting the anti-tumor function of CD8+ T and NK cells." (PMID 39135069, 2024). "By quantifying both PI9 inhibition and killing at single-cell resolution, we are able to demonstrate that while tumor cell PI9 overexpression does inhibits GZMB activity as expected, this inhibition surprisingly does not result in reduced cytotoxicity of CAR T cells." (PMID 38307835, 2024). "Furthermore, the endogenous inhibitor of GzmB, serine protease inhibitor 6, protects alloreactive T cells from GzmB-mediated mitochondrial damage without affecting graft-versus-tumor effect." (PMID 38846935, 2024). "Interestingly, B cell production of GZMB does not always equate to tumor killing; studies have found that IL-21-stimulated Bregs producing GZMB often coincide with Treg activity, indicating an immunosuppressive role." (PMID 39519376, 2024). "Similarly, in preclinical studies, the administration of human recombinant granzyme B in a perforin-independent manner to target HSP70-positive, undifferentiated colon cancer cells and 3D tumor spheroids induced caspase-3-mediated apoptosis in the tumor cells." (PMID 38994941, 2024). "Moreover, tumour-infiltrating T cells in tumours treated with both RMC-4998 and RMC-4550 showed marked activation, proliferation, and expression of potential anti-tumour cytotoxic molecules, such as TNFα, IFNγ and Granzyme B." (PMID 39322643, 2024). "Notably, in contrast to tumour tissue, we did not detect any GZMB+ cells among activated CD44+CD8+ T cells in tdLNs or spleen of tumour-bearing mice." (PMID 38658748, 2024). "Our study revealed that treatment with hsBCL9z96 significantly enhanced the proportions of IFN-γ+ CD8+, Granzyme B+ CD8+ and Ki67+ CD8+ T cells in tumor-infiltrating lymphocytes (TILs), as well as in tumor-draining lymph nodes (TdLN) and spleens from hsBCL9z96-treated CT26 tumor-bearing mice." (PMID 38811552, 2024). "However, we observed a significant improvement in NK cell function upon silencing circARAP2, manifested by rescued NK92 cell killing of K562 tumor cells and expression of effector molecules such as IFN-γ, Granzyme B, and CD107a in both rsMICA-treated NK92 and human activated NK cells." (PMID 39048814, 2024). "Additionally, in agreement with the results obtained with the B16-OVA model, the numbers of tumor-infiltrating CD45+, granzyme B- or IFNγ-producing CD8+ T cells and CD4+ T cells were significantly greater in the TOFA-treated Th9 group than in the untreated Th9 cell group." (PMID 39187636, 2024). "Histological evaluation using the region of interest (ROI) protocol showed that GzmB expression levels in CD8+ T cells were decreased in areas with high infiltration of CCR8+ Tregs, suggesting a suppressive effect of CCR8+ Tregs on T cell cytotoxicity in the local tumor microenvironment." (PMID 38783281, 2024).
tumor (continued). "B cells could promote the formation of immunosuppressive cells by releasing immunosuppressive cytokines, and also participate in the process of presenting tumor antigens to CD4 T and CD8 T cells, directly attacking tumor cells through Granzyme B, and are important anti-tumor cells." (PMID 38773226, 2024). "Moreover, a minor to medium increase of GZMB expression and upregulation of activation of CD69, IFN-γ, CD25 and CD107 were detected in tumor-infiltrating CD8+ T cells from the B16F10 tumor graft after silencing Mi-2β, which was strongly augmented by anti-PD-1 treatment." (PMID 38461299, 2024). "However, the variations in granzyme B+ B cells between tumor and non-tumor tissues have been largely unexplored." (PMID 38386050, 2024). "Similarly, after the application of camrelizumab, elevated expression of IFN‐γ and GzmB within CD8+ T cells was observed in the tumours with VISTAlow TAMs rather than VISTAhigh TAMs." (PMID 38356419, 2024). "We further found that the frequency and absolute counts of NK cell subset distribution and the percentage of granzyme B and perforin were not related to tumor stage, but the percentage and MFI of IFN-γ were significantly decreased with the progression of tumor stage." (PMID 38806640, 2024). "Moreover, treatment with crizotinib or αPD-1 alone promoted greater numbers of tumor-infiltrating CD8+ T cells, IFN-γ+granzyme B+CD8+ T cells, and T effector (Teff) subsets (Th1) of CD4+ T cells in tumors than did treatment with the vehicle but substantially fewer than did the combination treatment." (PMID 38307859, 2024). "Moreover, in comparison to the tumor-bearing controls, the PD-1 expressive CD8+ T cells was notably decreased, accompanied by a slightly reduced level of granzyme B after cryo-thermal therapy, indicating that CD8+ T cell-activation function of cryo-thermal therapy." (PMID 38827732, 2024). "Importantly, ex vivo analysis of tumor-infiltrating T cells that were identified by their congenic CD45.2 marker expression demonstrated strongly increased effector functions, such as granzyme B and IFN-γ expression, if the mice received T cells that were pretreated under high conditions." (PMID 39198632, 2024). "The binding of BCRs and tumor antigens not only increases the secretion of cytokines that induce the activation of CD4+ T cells, CD8+ T cells, and NK cells, but also directly kills tumor cells through the secretion of cytolytic molecules, such as GZMB and TRAIL." (PMID 38203530, 2023). "This is consistent with observations in tumor-infiltrating MAIT cells in CRC and GC patients, where exhausted MAIT cells (PD-1highTim-3+CD39+) became the dominant phenotype and exhibited greater penetration into CRC tissues, and MAIT cells showed reduced secretion of granzyme B molecule." (PMID 36463401, 2023). "More importantly, effector CD8+ T cells producing IFN-γ and granzyme B were significantly reduced in tumors and draining lymph nodes from Ccdc134 TKO mice, relative to WT mice, and Ccdc134 TKO CD8+ T cells expressed lower levels of Ki67 than WT controls in the tumor microenvironment." (PMID 37234153, 2023). "Some researchers have reported that GZMB is not involved in pDC-induced tumor cell killing." (PMID 37817484, 2023). "However, the peripheral serum IFNγ and granzyme B measurements did not closely reflect KD033 activity in the tumors as the magnitude of increases did not correlate to the observed anti-tumor activity levels." (PMID 36454338, 2023). "There was also intratumoral heterogeneity of these mechanisms, for example, the virtual absence of Granzyme B + iTILs in the tumor center when compared to other compartments or the presence of FOXP3 + TILs at the invasive margin but not in other tumor regions (patient 7)." (PMID 36562826, 2023).
tumor (continued). "Under hypoxia, tumor cells evade immune surveillance by T cells by inducing autophagy through HIF‐1α/STAT3 signaling, and hypoxia‐induced autophagy reduces NK cell killing by degrading the NK‐derived serine protease granzyme B (GZMB) during transport within cancer cells." (PMID 37860928, 2023). "To determine whether MARCH5 knockdown affects the activation of tumor-infiltrating CD8+ T cells or the profile of exhausted T cells, we examined the T cell activation maker Granzyme B (GzmB) and the exhausted T cell marker TIM3 on infiltrated CD8+ T cells in the mouse tumor models." (PMID 37932447, 2023). "Therefore, we determined the CD3+CD8+ T cell infiltration after pathological inspection with hematoxylin and eosin staining and mIF staining of T cell tumor infiltration markers (CD3, CD8, granzyme B (GrzB), Ki67, cytokeratin (CK) and DAPI) in one randomly selected macro-region tissue per patient." (PMID 37127787, 2023). "However, tumor-specific inhibition of glutamine uptake and glutaminase activity in combination with anti-PD-L1 therapy strongly induced CD8+ T cell proliferation and granzyme B production, while abating tumor growth." (PMID 37842241, 2023). "On the other hand, anti-tumour activity assessments with CPP33-functionalised polymersomes lacking granzyme B clearly demonstrated that the observed cell death was mainly due to the apoptotic activity of granzyme B and not a direct consequence of the cytotoxic effects of the CPP." (PMID 36537575, 2023). "Furthermore, in xenograft models, the enhanced tumor proliferation (Ki67) and decreased angiogenesis (CD31) due to MFAP5 overexpression in CAFs was also partially reverted by application of AMG487, along with increased Granzyme B+CD8+T cells infiltration." (PMID 37156839, 2023). "Moreover, Granzyme B (Gzm B) can cleave GSDME in an indirect manner by activating caspase-3, or it can also directly cleave GSDME to initiate pyroptosis, which provides a new therapeutic strategy for future tumor immunotherapy." (PMID 36823153, 2023). "Moreover, CD103+ TRM cell-derived granzyme B and IFN-γ in humans control tumor formation and metastasis through fibronectin secretion, facilitate the priming of newly generated tumor-specific T cells, and boost immune cell recruitment in the tumor." (PMID 36305904, 2022). "Interestingly, density of CD8+ and GZMB+ cells were of consistent prognostic value regardless of their tumour proximity, whereas CD68+ cell density had the greatest prognostic effect in the TP25μm zone and decreased in locations more distant to the tumour." (PMID 36114487, 2022). "Besides, significantly more CD8+/GzmB+ cells could be found in close proximity (≤50 μM radial distance) of PGRN−/PanCK+ cells, implying a potential regulatory role of PGRN in tumor immunogenicity and antitumor cytotoxicity in PDAC." (PMID 35013174, 2022). "In this work, we showed that treated tumors present a negative correlation in the spatial distribution of CD73 and Granzyme B + cells, suggesting therapies targeting CD73 may increase anti-tumor immunity throughout the tumor when impairing ADO pathway activation." (PMID 36147911, 2022). "Similarly, G-CSF did not alter ARI2h granzyme B levels, either basally or following stimulation with tumor cells." (PMID 35859694, 2022). "In addition, the combination treatment induced great increases in cleaved caspase‐3 and granzyme B compared with the other treatments in CT26‐EV allograft tumours, but these levels were not further enhanced in CT26‐SA14 allograft tumours." (PMID 35858011, 2022). "In the representative case (patient 3) with negative 68Ga-grazytracer PET/CT results after 1 cycle of pembrolizumab treatment, 68Ga-grazytracer imaging showed low tumor uptake in the whole body, indicating that there was no granzyme B secretion in any of the lesions." (PMID 35788116, 2022).
tumor (continued). "Here, we show that PET imaging using a granzyme B–targeted radiotracer named 68Ga-grazytracer, could noninvasively and effectively predict tumor responses to immune checkpoint inhibitors and adoptive T cell transfer therapy in multiple tumor models." (PMID 35788116, 2022). "In tumor patients with a relatively high level of neutrophils, T cell immune response is often reduced, as represented by the reduced expression of cytotoxic T cell genes including CD8A, CD8B, GZMA, and GZMB, the reduced number of CD3 + CD8 + cells, and the reduced expression of IFN-γ related genes." (PMID 36275807, 2022). "There was a significant increase (p<0.001) in the levels of IFN-γ, IL-2, granzyme B, and CD107a in CD8+ T cells, indicating that inhibition of PD-L1 secretion from tumor cells contributed to CD8+ T cell activation and could help restore CD8+ T cell proliferation." (PMID 35228265, 2022). "Notably, NK cell-derived extracellular vesicles (NK-EVs) including exosomes typically contain cytotoxic proteins (e.g. perforin, granzyme B, FasL, and TRAIL), originating from NK cells and induce anti-tumor activity against various cancers through the activation of caspase-dependent pathways." (PMID 36068970, 2022). "Moreover, granzyme B (GZMB) released from T cells can cleave GSDME directly or through Caspase-3 in target cells and activate extensive pyroptosis, further promoting antitumor immune response and inhibiting tumor growth." (PMID 35990696, 2022). "Using the MMTV-PyMT tumor model, the authors showed infiltration of precancerous lesions and tumors by three different populations with cytotoxic properties, TCRβ+ T cells, TCRδ+ T cells, and TCR- NK1.1+ NKp46+ innate lymphocytes, all of which express GzmB and share a similar transcriptome." (PMID 36372017, 2022). "Notably, the expression level of B7–H3 was negatively correlated with the expression of CD8+T-cell activity factors TNF-α, IFN-γ, perforin, and granzyme B, which could explain why high LINC01123 expression promotes tumor immune escape." (PMID 35115487, 2022). "In addition, we also found that the genes (GSDM, IRF1, GZMB, and CASP5, etc.)with a higher frequency of CNV have higher expression differences between normal and tumour tissues and greater correlation with prognosis, which further highlights the key role of CNV in GC." (PMID 35923703, 2022). "IK14004 enhances expression of both activating co-receptors in CD8+ T cells including granzyme B expression and, given the relevance of these co-receptors in cancer immunotherapy, we cannot exclude the possibility of an indirect immune-related effect of IK14004 on tumour growth." (PMID 35778468, 2022). "In concurrence with NanoString analysis of our own tumor samples, these included IFN-γ signaling genes STAT1, CXCL10, and IDO1; antigen presentation molecules HLA-DQA1 and HLA-DRB1; important T cell molecules GZMB and IL7R; and B cell–related molecules CD79A and CXCL13." (PMID 35132960, 2022). "Hence, there is an optimal period of time for detecting granzyme B secreted from effector T cells that have not yet been transported into tumor cells, which can be effectively achieved by 68Ga-grazytracer PET." (PMID 35788116, 2022). "Furthermore, interrogation of the HIS in immune organs and tumors by flow cytometry revealed increased Granzyme B+, TNFα+ and IFNγ+ CD4+ T cells among the human tumor infiltrating leukocytes (TIL) that correlated with reduced tumor growth in the combination-treated HIS-mice." (PMID 36419897, 2022). "Given the role of granzyme B in the exertion of CTL function during immunotherapy, a granzyme B-targeting radiotracer, 68Ga-NOTA-GZP, and its analog, 18F-AlF-mNOTA-GZP, have recently been developed for noninvasive monitoring of tumor responses to ICIs in preclinical studies." (PMID 35788116, 2022).
tumor (continued). "As tumor targets, we used the reporter HeLa cell line stably transduced with the NES-ELQTD-GFP-T2A-NES-VGPD-mCherry construct, leading to the equimolar expression of two fluorescent reporters: Granzyme B-sensitive nuclear export signal (NES) fused to mCherry and Caspase-8-sensitive NES fused to GFP." (PMID 35300331, 2022). "The negative correlation observed in E0771 tumors between TNF-α expression on day 12 and granzyme B on day six indicates that the cell-mediated (i.e., Th1) response is transient and not sustained by day 12 when physical changes in tumor volume due to IMT were noted." (PMID 35214172, 2022). "Furthermore, as granzyme B secretion is a characteristic of various immune-related disorders, 68Ga-grazytracer PET may prove effective in contexts beyond tumor imaging." (PMID 35788116, 2022). "In congruence with similar studies, our investigation into the utility of granzyme B tracking with GZP-PET revealed that it is a useful, real-time molecular imaging approach for imaging the adaptive immune response and evaluating individual tumor response to treatment." (PMID 35214172, 2022). "Interestingly, senescent T cells can function like natural killer (NK) cells to kill tumor cells independent of TCR by secreting granzyme B and perforin." (PMID 35875098, 2022). "Because GZMB is an identified marker with the strongest cytotoxic capacity toward target cells, these results indicate that PF543 treatment may increase the tumor-specific CD8+ CTL population in the TME." (PMID 36050478, 2022). "The expression levels of the checkpoint inhibitory molecule PD-1, the cell activation marker CTLA-4, the cytotoxic molecule granzyme B, and the cell proliferation marker Ki-67 by tumor infiltrating and splenic CD8+ and CD4+ T cells were not different between the groups." (PMID 35514996, 2022). "Indeed, we found that intratumoral NK cells and CD8 T cells in mice received expanded Vam6+/− iNKT cells produced more granzyme B than those cells in mice received expanded Vam6+/+ iNKT cells, indicating a contribution of NK cells and CD8 T cells in enhanced tumor clearance." (PMID 36741382, 2022). "In addition to increasing the synthesis of chemokines at the tumor site and the penetration of these CAR-T cells into cancerous cells, chemotherapy also makes the tumor cells more sensitive to granzyme B, allowing it to infiltrate the layer of tumor cells more readily." (PMID 36419058, 2022). "Moreover, tumor-infiltrated CD8+ effector T cells were more efficiently activated by VV-EpCAM BiTE injection than by VV-Ctrl injection or PBS injection, as evidenced by the enhanced expression of IFN-γ, granzyme B and TNF-α." (PMID 36451817, 2022). "Moreover, in an in vitro co-culture system, knockdown of PRMT5 in tumor cells could directly enhance the expression of IFN-γ, TNF-α and granzyme B in T cells." (PMID 34522232, 2021). "However, the frequencies of CD8+ and CD4+ T cells expressing the cytotoxic molecules granzyme B or perforin were not elevated in the tumor or spleen of the anti-HVEM group." (PMID 34208480, 2021). "Thus, the increase in CD8+ T cells expressing Granzyme B reflects a specific activation of tumor-infiltrating T cells, even when non-differences in CD8+ T cell numbers were observed across treatments." (PMID 33849551, 2021). "In addition, tumor-bearing mice treated with anti-PVRIG mAb showed lower frequency of tumor-infiltrating CD8+ T cells expressing inhibitory receptor CD96 and higher frequency of tumor-infiltrating CD8+ T cells expressing NKG2D, TRAIL, CD107a, GzmB and IFN-γ." (PMID 34174928, 2021). "Intracellular flow cytometry-based analysis of tumor-infiltrating T cells from Vaccine/Bintrafusp/SX-treated mice revealed significantly higher frequencies of proliferative (CD8+ Ki67+) and cytotoxic (CD8+ Granzyme B+) TIL compared to tumors in the Bintrafusp/SX and Control groups." (PMID 33669155, 2021).